FH (fumarate hydratase)
Diseases named in the same sentence as FH in open-access papers (continued):
Sharing a sentence is not in itself a finding about the gene and the disease.
renal cell carcinoma (continued). "Different DNA methylation has previously been shown in FH-deficient renal cell carcinoma (RCC)." (PMID 38721148, 2024). "The histopathology was consistent with renal cell carcinoma with features of FH-deficient variant." (PMID 37992668, 2023). "Strikingly, both of these individuals had FH‐deficient renal cell carcinoma." (PMID 32463173, 2020). "However, the role of XBP1 in the progression of FH mutated renal cell carcinoma has been unrecognized." (PMID 32774853, 2020). "Interestingly, hereditary heterozygous mutations in another TCA cycle enzyme, fumarate hydratase (FH), also lead to the development of renal cell carcinomas following the loss of heterozygosity, similarly to VHL or SDH mutations." (PMID 29772792, 2018). "Mutations in FH genes have been found in cutaneous and uterine leiomyomatas and renal cell cancer." (PMID 29342092, 2018). "Anti‐VEGF drugs such as lenvatinib or bevacizumab combined with immunotherapy or EGFR inhibitors have shown encouraging results in FH‐deficient renal cell carcinoma, suggesting that they may also derive some benefit for patients with FH‐deficient Leydig cell tumours." (PMID 41384702, 2026). "Mutations in the FH gene have been implicated in the development of renal cell carcinoma (RCC), as well as in ovarian and Leydig cell cancers." (PMID 40863132, 2025). "FH-deficient renal cell carcinoma (RCC) is associated with HLRCC syndrome, which is characterized by FH germline mutation or bi-allelic cell FH deletion without germline mutation." (PMID 38974045, 2024). "Succinate dehydrogenase (SDH)-deficient renal cell carcinoma (RCC) and fumarate hydratase-deficient RCC (FH-deficient RCC) were implicated." (PMID 38793008, 2024). "In addition, the positive rate of 2SC in FH-deficient renal cell carcinoma was 100%, and the positive manifestations were strong positive in diffuse nucleus and cytoplasm, which could be used for auxiliary diagnosis of FH-deficient renal cell carcinoma." (PMID 38974045, 2024). "In addition, an aggressive subtype of renal cell carcinoma caused by mutations in the FH gene is Fumarate hydratase (FH)-deficient renal cell carcinoma (FHdRCC), which can lead to fumarate accumulation, resulting in the activation of HIF through the inhibition of prolyl hydroxylases." (PMID 37601653, 2023). "Fumarate hydratase (FH)-deficient renal cell carcinoma (RCC) is a distinct entity, which shows a biallelic inactivation of the FH gene that consequently leads to FH protein expression and function loss, respectively." (PMID 34448900, 2021). "Fumarate hydratase-deficient renal cell carcinoma (FH-RCC) is a subtype of RCC that is increasingly recognized pathologically." (PMID 33608050, 2021). "FH-deficient RCC often shows a morphologically overlapping spectrum with papillary renal cell carcinoma (type 2), whereby a typical mixture of growth patterns including tubulo-cystic, cribriform, and/or solid differentiation can be observed." (PMID 34448900, 2021). "Notably, ABL1 plays a critical role in an aggressive form of hereditary kidney cancer observed in patients with a germline mutation in the enzyme fumarate hydratase (FH) that leads to the development of hereditary leimyomatosis and renal cell carcinoma (HLRCC)." (PMID 34022881, 2021). "On the other hand, inactivating mutation of FH (an enzyme involved in the mitochondrial tricarboxylic acid cycle) causes Nrf2-dependent activation of antioxidant pathways in patients with inherited type 2 pRCC (pRCC2) or hereditary leiomyomatosis and renal cell carcinoma (HLRCC)." (PMID 31752777, 2019). "Indeed, mutations in either fumarate hydratase (FH) or succinate dehydrogenase (SDH B, C and D), both enzymes of the TCA cycle, are known to promote different cancer types, from leiomyoma, leiomyosarcoma and renal cell carcinoma (FH mutations) to paraganglioma and pheochromocytoma (SDH mutations)." (PMID 27083002, 2016).
renal cell carcinoma (continued). "In certain cancers, such as renal cell carcinoma with hereditary leiomyomatosis (HLRCC), loss-of-function mutations in fumarate hydratase (FH) lead to accumulation of fumarate." (PMID 41356199, 2026). "Fumarate hydratase (FH) is a crucial enzyme in the tricarboxylic acid cycle (TCA), and its loss is implicated in various cancers, notably in renal cell carcinoma (RCC)." (PMID 41427347, 2025). "FH gene heterozygous mutation predisposes individuals to HLRCC syndrome, which increases the risk for developing multiple leiomyomas as well as renal cell carcinoma." (PMID 40002168, 2025). "Cancer risk in patients with FH deficiency is significant, due to its key role in HLRCC syndrome and in the lifetime risk of developing renal cell carcinoma (as high as 15–30%)." (PMID 40002168, 2025). "Fumarate hydratase-deficient renal cell carcinoma (FH-RCC) is a rare subtype of kidney tumor." (PMID 39555225, 2024). "Heterozygous mutations in the FH gene can lead to FH-deficient RCC, predisposing individuals to aggressive forms of renal cell carcinoma and other tumors." (PMID 38974045, 2024). "We detected a complex SV with a breakpoint in the in the final intron of FH, consistent with leiomyomatosis and renal cell cancer (MIM: 150800)." (PMID 38776926, 2024). "Several investigations have reported the presence of FH protein deficiency in various types of renal cell cancer, including tubulocystic carcinoma with dedifferentiated foci, type 2 RCC, unclassified high-grade RCC, and collecting duct carcinoma." (PMID 38765391, 2024). "The germline heterozygous mutation of the FH gene results in HLRCC including multiple cutaneous, uterine leiomyomas and renal cell carcinomas." (PMID 35163394, 2022). "A tenuous analogy can be drawn to renal cell carcinomas, which similarly acquire high burdens of truncating mutations to complex I and biallelic alterations to the TCA cycle enzymes SDHB and FH." (PMID 35731870, 2022). "This case reported one of the features of metastasis of renal cell carcinoma with FH gene deletion of a male patient 7 months after undergoing radical nephrectomy." (PMID 36330469, 2022). "There had been few reports about ultrasonographic imaging of metastasis of renal cell carcinoma with FH gene deletion." (PMID 36330469, 2022). "Ultrasonographic findings of masses in the retroperitoneum and abdominal wall are fully discussed, which have been confirmed by biopsy and diagnosed as renal cell carcinoma with FH gene deletion by pathology." (PMID 36330469, 2022). "Germline mutations within the Krebs cycle enzyme genes fumarate hydratase (FH) or succinate dehydrogenase (SDHB, SDHC, SDHD) are associated with an increased risk of aggressive and early metastasizing variants of renal cell carcinoma (RCC)." (PMID 36455002, 2022). "For example, the inactivation of fumarate hydratase (FH) or succinate dehydrogenase (SDH) in some forms of renal cell carcinomas (RCCs) result in the direct interruption of the tricarboxylic acid (TCA) cycle and oxidative phosphorylation (OXPHOS)." (PMID 36142502, 2022). "Fumarate hydratase deficient renal cell carcinoma (FH-RCC) is a rare subtype of RCC." (PMID 33608050, 2021). "The function of ASL can be regulated by fumarate hydratase expression in renal cell carcinoma and by epigenetic modulation in glioblastoma." (PMID 28969007, 2017). "Germline mutations in the fumarate hydratase (FH) gene predispose individuals to hereditary leiomyomas and renal cell cancer (HLRCC), which occurs in about 20% of overall renal cell carcinoma (RCC)." (PMID 28977985, 2017). "Recent discoveries revealed activating mutations in MET oncogene and inactivating mutation in Fumarate Hydratase (FH) gene in the hereditary papillary renal carcinoma (HPRC) and hereditary leiomyomatosis and renal-cell cancers (HLRCC), respectively." (PMID 29285223, 2017).
renal cell carcinoma (continued). "Other TCA cycle enzymes involved in cancer are succinate dehydrogenase (SDH) in hereditary paragangliomas and gastrointestinal stromal tumour (GIST), and fumarate hydratase (FH) in hereditary leiomyomas and renal cell cancer (HLRCC)." (PMID 28484589, 2017). "Mutations in fumarate hydratase (FH), an enzyme in the TCA cycle that follows SDH, have been associated with multiple cutaneous leiomyomas, uterine leiomyomas and aggressive renal cell carcinomas." (PMID 26462158, 2015). "Loss-of-function germline mutations in tumor suppressor genes encoding the Krebs cycle enzymes fumarate hydratase (FH) and succinate dehydrogenase (SDH) have been identified in some forms of human renal cell cancer, paraganglioma, and pheochromocytoma." (PMID 25980580, 2015). "Targets of Hsa-miR-200b-3p were involved in several pathways like renal cell carcinoma, associated to some oncogenes such as MET, or tumors suppressors like VHL, FH and BHD." (PMID 23372853, 2013). "Recent studies using renal cell carcinoma cells showed roles of mutant fumarate hydratase (FH) in their development." (PMID 22331189, 2012). "For example, fumarate hydratase (ko:K01679) is involved in the renal cell carcinoma pathway, as well as in the citrate cycle, a fundamental pathway present in most bacteria." (PMID 19680427, 2009). "This case illustrates the practical challenges faced in treating fumarate hydratase-deficient renal cell carcinoma, including the lack of established systemic treatment guidelines and management of treatment-related adverse events." (PMID 41789002, 2026). "In patients with germline FH mutations, dFH-LM may be the first manifestation of HLRCC, a syndrome associated with aggressive renal cell carcinoma that requires early genetic counseling and surveillance." (PMID 41374387, 2025). "In the 2022 edition of WHO, it was pointed out that FH somatic mutations may also lead to the development of this type of renal cell carcinoma, and have extremely similar biological behaviors to HLRCC caused by FH germline mutations." (PMID 39659780, 2024). "Our study suggested that immunotherapy is an effective therapeutic option for patients with HLRCC-rcc regardless of the type of FH germline mutation." (PMID 39160519, 2024). "Twenty-five (40%) participating uropathologists have encountered low-grade oncocytic renal neoplasms that are deficient for fumarate hydratase (FH, mimicking SDH-deficient renal cell carcinoma), typically within consultation practice, whereas 35 (56%) have not (Question #27)." (PMID 39287823, 2024). "Studies on renal cell carcinoma and LPS‐stimulated macrophages have demonstrated the extensive physiological and pathological background and application potential of fumarate accumulation driven by FH inhibition." (PMID 37426680, 2023). "Although more than twenty years have passed since its discovery as the leading cause of the cancer syndrome Hereditary leiomyomatosis and Renal Cell Carcinoma (HLRCC), it is still unclear how the loss of FH causes cancer in a tissue-specific manner and with such aggressive behaviour." (PMID 37689804, 2023). "FH-deficient RCC shows a pathogenic germline FH mutation, with negative FH and/or positive 2SC protein expression, but other subtypes of renal cell carcinoma show positive expression of the FH protein, with no inactivated mutation of the FH gene." (PMID 37076922, 2023). "A well-established example in gliomas is isocitrate dehydrogenase (IDH), which converts isocitrate to α-KG, mutations have also been found in succinate dehydrogenase (SDH) and fumarate hydratase (FH) in other conditions including phaeochromocytoma, paraganglioma, and renal cell carcinoma." (PMID 36643416, 2022). "Renal cell carcinoma with FH gene deletion is a rare subtype of renal cell carcinoma." (PMID 36330469, 2022).
renal cell carcinoma (continued). "Here we present a case of a 42-year-old female having isolated renal cell carcinoma, papillary type 2, carrying a mutation in the FH gene without cutaneous and uterine involvement." (PMID 35919231, 2022). "In this report we show by RNAseq that addition of the amino acid asparagine to cell culture medium containing glutamine triggers the UPR in an FH-deficient renal cell carcinoma cell line but not in the FH-repleted control cell line." (PMID 32774853, 2020). "In the current study, we aimed to validate the effect of genetic and pharmacological inhibition of HO-1 in cells isolated from patients suffering from hereditary leiomyomatosis and renal cell carcinoma (HLRCC)—an inherited cancer syndrome, caused by FH deficiency." (PMID 31963199, 2020). "Additionally, LOF mutations in succinate dehydrogenase (SDH) and fumarate hydratase (FH) have been found in paragangliomas and pheochromocytomas, and leiomas and renal cell cancer, respectively." (PMID 29342092, 2018). "Interestingly; unlike IDH3, inactivation of other TCA enzymes like succinate dehydrogenase (SDH) and fumarate hydratase (FH) have been reported in cancer, including paraganglioma and renal cell carcinomas." (PMID 28785398, 2017). "Heterozygous germline fumarate hydratase (FH) mutations have been demonstrated to be associated with an autosomal dominant disease named multiple cutaneous and uterine leiomyomatosis (MCUL), as well as a rare disorder known as hereditary leiomyomatosis and renal cell carcinoma (HLRCC)." (PMID 38790186, 2024). "Its (bi-allelic) mutation and/or deletion is considered the main molecular event in FH-deficient RCC, formerly classified as hereditary leiomyomatosis and renal cell carcinoma RCC (HLRCC-RCC)." (PMID 37999735, 2024). "A high frequency of somatic mutations in IDH1 (isocitrate dehydrogenase 1), FH (fumarate hydratase), as well as SDH A–D and F (succinate dehydrogenase) genes is observed in gliomas, hepatobiliary cancers, neuroendocrine carcinomas, renal cell carcinomas, and melanomas." (PMID 37873808, 2023). "Moreover, immunohistochemistry targeting fumarate hydratase (FH) has been proven as an efficient method to pinpoint rare FH gene germline mutations in PPGL, in turn coupled to the hereditary leiomatosis and renal cell carcinoma (HLRCC) syndrome." (PMID 33768452, 2021). "Although we cannot exclude the possibility that methylation of regions other than the proximal promoter may be involved, our findings are also in keeping with others who have been unable to demonstrate methylation of SDHD in neuroblastomas and FH in renal cell cancers." (PMID 19778456, 2009). "Metabolic studies reveal that FH, a key TCA cycle enzyme, exhibits significant tumor‐suppressive functions in renal cell carcinoma (RCC)." (PMID 40919133, 2025). "Risk factors and comorbidities might be associated to renal cell carcinoma, while a small fraction of 2–3% emerges from patients with predisposing cancer syndromes, typically associated to hereditary mutations in VHL, folliculin, fumarate hydratase or MET genes." (PMID 38512353, 2024). "Genomic studies identifying the genes for kidney cancer, including the VHL, PBRM1, MET, FLCN, fumarate hydratase, succinate dehydrogenase, TSC1, TSC2, and TFE3 genes are known to play role in renal cell carcinoma development." (PMID 35709632, 2022). "If the internal control was positive, but FH staining was completely absent in the cytoplasm of the tumor cells, it was considered to be true FH-negative, and this kind of renal cell carcinoma was classified as FH-RCC." (PMID 39555225, 2024). "The cited authors report that VHL, BAP1, FH, and MET are specific genes that increase the risk of developing renal cell cancer, whereas CHEK2, MUTYH, APC, and STK1 are not typically associated with the development of renal tumours." (PMID 39336594, 2024). "The majority of the genes involved in hereditary renal cell carcinoma (RCC) are HRPT2, FH, BHD, MET, VHL, and FH." (PMID 38666938, 2024).
renal carcinoma (71 papers, 2007 to 2025). A carcinoma arising from the epithelium of the renal parenchyma or the renal pelvis. "Human SDH-mutant paraganglioma/pheochromocytoma and FH-deficient renal cancers show SDH/FH-linked hypermethylation and pseudohypoxia signatures, directly tying mitochondrial TCA lesions to epigenetic remodeling in vivo." (PMID 41154717, 2025). "Previous studies have shown that FH-deficient renal cancer cells exhibit impaired oxidative phosphorylation and increased aerobic glycolysis." (PMID 41008787, 2025). "The occurrence of RC is also known to support cancer cell growth by sustaining the production of anabolic Krebs cycle metabolites in cancer cells under hypoxia or in cells with a defective Krebs cycle such as FH-mutated renal carcinoma cells." (PMID 40209948, 2025). "Genetic examination for the mutation of the fumarate hydratase gene is important in order to reach the correct diagnosis and to detect renal cancer at its early stage." (PMID 38928693, 2024). "FH-deficient RCC is a rare and aggressive subtype of renal cancer, resulting from pathogenic mutations in the fumarate hydratase gene." (PMID 39282017, 2024). "Fumarate accumulation is well described as a driver of tumour aggressiveness in renal cancers that are fumarate hydratase-deficient, due to loss of heterozygosity of the enzyme or upregulation of the mammalian target of rapamycin (mTOR)." (PMID 36631900, 2023). "We demonstrate regional metabolic heterogeneity within human tumors, document the impact of fumarate hydratase deficiency in human renal cancers, and investigate the contributions of TCA cycle turnover and CO2 recycling to isotope labeling in vivo." (PMID 37611583, 2023). "Fumarate hydratase (FH)-deficient RCC is a rare subtype of renal cancer that was considered a subtype of PRCC in the previous classification of RCC." (PMID 37367052, 2023). "FH-deficient RCC is a highly aggressive renal cancer and shows quite variable morphology; it can have prominent papillary architecture and oncocytic cytoplasm mimicking PRNRP." (PMID 35936734, 2022). "Type1 and Type2 papillary renal cell carcinomas are two different types of renal cancer, where Type2 papillary renal cell carcinoma is caused by germline mutation of the FH." (PMID 35382567, 2022). "When the TCA cycle enzyme fumarate hydratase (FH) is ablated in renal cancer, fumarate accumulates in the cell, which causes the EMT-suppressing miRNA miR-200 to be epigenetically silenced, allowing EMT-TFs to be activated." (PMID 35736645, 2022). "The retrograde signaling initiates the loss of heterozygosity (LOH) observed in the carcinoma patients' leiomyomatosis and renal carcinomas due to germline FH mutations." (PMID 34717757, 2021). "Isotope tracer studies in FH-deficient renal cancer cells showed that the contribution of glucose-derived carbon to TCA cycle is very limited, whereas glutamine-derived carbon enters the TCA cycle through reductive carboxylation of α-ketoglutarate." (PMID 32751108, 2020). "In a similar fashion, accumulating fumarate induced hypermethylation of a class of anti-metastatic miRNAs (miR-200) in fumarate hydratase (FH)-deficient renal cancer cells." (PMID 30809153, 2019). "Recent study also showed that accumulation of metabolites of Kreb’s tricarboxylic acid cycle in tumor cells caused epithelial-to-mesenchymal transition and renal cancer cells became aggressive when oncometabolite fumarate accumulated due to FH deficiency." (PMID 28785178, 2017). "Mutation or loss of fumarate hydratase (FH) can predispose cells to oncogenic transformation and cyst formation leading to renal cancer and renal cysts, respectively." (PMID 28491867, 2017). "In our recent work, we have shown that, by virtue of its epigenetic function, fumarate contributes to the invasive features of FH-deficient renal cancers." (PMID 27886164, 2017).